SRSF4 (serine and arginine rich splicing factor 4)
Description:
Plays a role in alternative splice site selection during pre-mRNA splicing. Represses the splicing of MAPT/Tau exon 10.
Synonyms: SFRS4; SRP75
Tractability: PROTAC: ubiquitination databases record sites on it; its protein half-life has been measured.
Gene: Protein-coding gene on chromosome 1 (29,147,743 to 29,181,922, reverse strand). Ensembl gene ENSG00000116350.
Subcellular location: Nucleus speckle
Subcellular location (Human Protein Atlas): Nuclear speckles
Pathways (Reactome):
Metabolism of RNA: Processing of Capped Intron-Containing Pre-mRNA; Transport of Mature mRNA derived from an Intron-Containing Transcript; mRNA 3'-end processing; mRNA Polyadenylation; mRNA Splicing - Major Pathway
Disease: Dengue Virus-Host Interactions
Gene Ontology:
Molecular function: protein binding; RNA binding; nucleic acid binding; sequence-specific mRNA binding
Biological process: negative regulation of mRNA splicing, via spliceosome; mRNA processing; regulation of alternative mRNA splicing, via spliceosome; RNA splicing; RNA splicing, via transesterification reactions; response to insulin
Cellular component: nuclear speck; nucleoplasm; nucleus
Genetic constraint (gnomAD): Loss-of-function variants: 5 observed, 33.94 expected, observed/expected ratio (o/e) 0.15, 90% interval 0.076 to 0.31. The upper end of that interval is the gene's LOEUF score, 0.31, which puts it in group 1 of 6, group 1 being the genes least tolerant of losing a copy. Missense variants: 286 observed, 483.67 expected, observed/expected ratio (o/e) 0.59, 90% interval 0.54 to 0.65. Synonymous variants: 173 observed, 163.11 expected, observed/expected ratio (o/e) 1.06, 90% interval 0.94 to 1.2.
Homologues: Orthologues: chimpanzee SRSF4 (99% identical), macaque SRSF4 (95% identical), guinea pig SRSF4 (93% identical), pig SRSF4 (93% identical), rat Srsf4 (89% identical), mouse Srsf4 (87% identical), rabbit SRSF4 (69% identical), dog SRSF4 (54% identical), tropical clawed frog srsf4 (53% identical), zebrafish srsf4 (48% identical), Drosophila melanogaster B52 (41% identical), Caenorhabditis elegans rsp-1 (31% identical). Paralogues in human: SRSF6 (49% identical), SRSF5 (34% identical), SRSF1 (23% identical), SRSF7 (21% identical), SRSF9 (18% identical), RSRC2 (17% identical), SRSF3 (16% identical), RSRP1 (15% identical).
Diseases named in the same sentence as SRSF4 in open-access papers:
SRSF4 is named in the same sentence as 36 diseases in open-access papers, as found by Europe PMC text mining. Sharing a sentence is not in itself a finding about the gene and the disease. The quoted sentences say what the papers report.
breast carcinoma (8 papers, 2013 to 2023). "SRSF4 plays a role in breast cancers and regulates splicing of some mechanosensitive proteins in striated muscle." (PMID 36123433, 2022). "Thus, the expression of SRSF4 is related to the therapeutic benefit of cisplatin, and changes in transcripts and splicing related to SRSF4 confer breast cancer cells with anti-cisplatin activity." (PMID 29789787, 2018). "The implication of splicing factors SRSF4, SRSF6 and TRA2β was already demonstrated in cell proliferation and invasion promotion in normal mammary cells and in breast cancer cells." (PMID 37904233, 2023). "A similar reduction of the cisplatin-induced HNRNPDL exon 6 exclusion and exon 8 inclusion after knock-down of SRSF4 was observed in the breast cancer cell line BT549 (not illustrated)." (PMID 25884497, 2015). "Additionally, among splicing regulators frequently altered in breast cancers (in >5% of tumors), we found different members of SR protein family (such as SRSF1, SRSF2, SRSF3, SRSF4, SRSF6, SRSF9, SRSF10, SRSF11) with at least one predicted binding motif in the CD44 v10 region." (PMID 33143085, 2020).
acute myeloid leukemia (4 papers, 2018 to 2022). Acute myeloid leukemia (AML) is a group of neoplasms arising from precursor cells committed to the myeloid cell-line differentiation. "In newly diagnosed acute myeloid leukemia (AML) patients, SRSF4 mRNA was found significantly decreased in peripheral blood mononuclear cells (PBMCs)." (PMID 35463320, 2022).
hepatocellular carcinoma (3 papers, 2008 to 2021). A malignant tumor that arises from hepatocytes. "Considering the other splicing machinery gene, SFRS4 (serine and arginine rich splicing factor 4), some authors earlier demonstrated that its mRNA level is stable in hepatocellular carcinoma (HCC) cell lines and patients with alcoholic liver disease." (PMID 30881377, 2019).
Alzheimer disease (2 papers, 2025). A progressive, neurodegenerative disease characterized by loss of function and death of nerve cells in several areas of the brain leading to loss of cognitive function such as memory and language. "Furthermore, alterations in SRSF4 function have been associated with systemic autoimmunity and neurodegenerative disorders, including Alzheimer’s disease in people with DS." (PMID 40662804, 2025). "One locus overlapped with a known Alzheimer's disease GWAS locus (EED/PICALM) and 2 with GWAS loci for circulating ω-3 fatty acids (SRSF4 and PSMG1)." (PMID 40949174, 2025).
frontotemporal dementia (2 papers, 2022 to 2023). Frontotemporal dementia (FTD) comprises a group of neurodegenerative disorders, characterized by progressive changes in behavior, executive dysfunction and language impairment, as a result of degeneration of the medial prefrontal and frontoinsular cortices. "Splicing factor SRSF4 is associated with frontotemporal dementia and Huntington’s disease and may have potential roles in AD pathology through tau." (PMID 37710351, 2023). "SRSF4, serine/arginine-rich splicing factor 4, interacting with heterogeneous nuclear ribonucleoproteins hnRNPG and hnRNPE2, regulates the 5’ splice site of tau exon 10; splicing misregulation could lead to frontotemporal dementia (FTD) in humans." (PMID 36614124, 2022).
osteosarcoma (2 papers, 2022 to 2024). A usually aggressive malignant bone-forming mesenchymal neoplasm, predominantly affecting adolescents and young adults. "We identified 6 splicing factor genes associated with the prognosis of osteosarcoma patients, namely SRSF1, SRSF4, SRSF5, SRSF7, SRSF8, and SRSF10." (PMID 39286028, 2024).
bone marrow failure (1 paper, 2024). "Herein, we describe a case of a boy with leuko-neutropenia secondary to bone marrow failure carrying a variant of the SRSF4 gene." (PMID 38396760, 2024). "The role of SRSF proteins in regulating mitochondrial activity has already been shown for SRSF6, but SRSF4 altered expression has never been reported as a cause of bone marrow failure." (PMID 38396760, 2024). "Although we have not found a direct relation between this genetic defect and bone marrow failure, our results support the hypothesis that the SRSF4 mutation could substantially contribute to the clinical phenotype observed in our patients." (PMID 38396760, 2024).
bone marrow failure syndrome (1 paper, 2024). "Since mitochondrial function is crucial for hematopoietic stem cell maintenance and some genetic bone marrow failure syndromes display mitochondrial defects, the SRSF4 mutation could have substantially contributed to the clinical phenotype of our patient." (PMID 38396760, 2024).
cystic fibrosis (1 paper, 2020). Autosomal recessive disorder caused by pathogenic variants in the CFTR gene (cystic fibrosis transmembrane conductance regulator), which encodes a chloride and bicarbonate channel expressed in epithelial cells, and follow the diagnosis criteria. "For example, SRSF1 (SF2/ASF), SRSF4 (SRp75), SRSF5 (SRp40), and SRSF6 (SRp55) are able to bind an ISS located in the intron 9 of the CFTR transcript and to skip the exon 9 causing the production of a nonfunctional protein associated with cystic fibrosis development." (PMID 32596243, 2020).
heart failure (1 paper, 2018). Inability of the heart to pump blood at an adequate rate to meet tissue metabolic requirements. "The expression of SRSF4 is decreased in patients with heart failure, and markers of heart failure, that is, brain natriuretic peptide and β cardiac myosin heavy chain, are increased in cardiomyocytes in Nkx2.5-Cre transgenic mice with SRSF4 knockout." (PMID 29789787, 2018).
hypertrophic cardiomyopathies (1 paper, 2019). "Finally, while conditional cardiac Srsf1 knockout animals die postnatally from defective juvenile-to-adult heart remodeling, conditional cardiac knockouts of Srsf2 (SC35) and Srsf4 (Srp75) are viable but develop dilated and hypertrophic cardiomyopathies, respectively." (PMID 31791406, 2019).
left ventricular hypertrophy (1 paper, 2018). Enlargement of the LEFT VENTRICLE of the heart. "Moreover, in these mice, RNA-seq analysis showed that SRSF4 knockout altered the expression of genes related to the metabolic pathway, transport, and cytoskeleton organization, suggesting that SRSF4 may be implicated in left ventricular hypertrophy." (PMID 29789787, 2018).
leukopenia (1 paper, 2024). "An 8-year-old patient admitted to the hematology unit because of leukopenia, lymphopenia, and neutropenia showed a missense variant of unknown significance of the SRSF4 gene (p.R235W) found via whole genome sequencing analysis and inherited from the mother who suffered from mild leuko-neutropenia." (PMID 38396760, 2024).
muscular disease (1 paper, 2022). Myopathy is a peripheral nervous system disease consisting of any abnormal condition or disease of the muscular tissues; commonly designates a disorder involving skeletal muscle. "Identifying SRSF4 as a mechanosensitive RNA-binding protein that might contribute to crosstalk between mechanotransduction, transcription, and splicing could potentially reveal novel insights into muscular diseases, particularly those with unknown etiologies." (PMID 36123433, 2022).
neutropenia (1 paper, 2024). A decrease in the number of neutrophils found in the blood. "In our patient, the strongly suggestive family history and a long-lasting leuko-neutropenia induced us to perform a deep genetic work up, revealing the presence of a variant of SRSF4 never reported in subjects with hematological diseases." (PMID 38396760, 2024).
pancreatic cancer (1 paper, 2025). "The inhibitor effectively suppressed the activity of SR proteins, SRSF4 and SRSF6, disrupting the RNA splicing process and inhibiting the growth and proliferation of the pancreatic cancer cells." (PMID 40126184, 2025).
Sleep apnea (1 paper, 2025). An intermittent cessation of airflow at the mouth and nose during sleep is known as sleep apnea. "Though the gene with the highest loading on LV3, SRSF4, has not been previously associated with sleep apnea, the second and third highest loading genes, PIGT and PRPS1, were included in the HPO sleep apnea gene set." (PMID 40662804, 2025).
cancer (11 papers, 2007 to 2025). A tumor composed of atypical neoplastic, often pleomorphic cells that invade other tissues. "We showed that the reprogramming of splicing induced by cisplatin makes a large contribution to its anti-cancer property, and that its action requires class I PI3K p110β and the splicing factor SRSF4." (PMID 25884497, 2015). "Furthermore, the presence of SRSF4-RFP, SYNCRIP-GFP, and SNU13-GFP in extracellular vesicles was confirmed through flow cytometry analysis of CD9 positive extracellular vesicles from dying cancer cells." (PMID 38898005, 2024). "However, when specific to certain cancer types or genes, this negative correlation did not hold, such as SRSF1 in LUSC and KICH; SRSF4 in TGCT, and SRSF5 in LAML and MESO (p < 0.05)." (PMID 38015716, 2023).
tumor (5 papers, 2007 to 2024). "Overall, siRNA-mediated knockdown of CBX6, CNOT6L, and SRSF4 consistently enhanced NT5E surface levels in various human tumor cell lines." (PMID 37409119, 2023). "In all three tumor classes the inclusion of these exons in SRSF4 and SRSF5 are lower than in NBS (−1 in Tumors), an indication of stabilization of these SRSF transcripts in the tumors." (PMID 28717182, 2017).
cardiovascular diseases (1 paper, 2021). "At least 6 critical genes, namely CTNNB1, HNRNPA1, SRSF4, TRA2A, SFPQ, and RBM5, and two large clusters of biological terms which are associated with the cardiovascular diseases are deregulated in the presence of omeprazole." (PMID 34659661, 2021).
hematological diseases (1 paper, 2024). "Among this protein family, the involvement of SRSF4 has already been reported in the setting of hematological diseases." (PMID 38396760, 2024).
infection (1 paper, 2025). The state of being infected such as from the introduction of a foreign agent such as serum, vaccine, antigenic substance or organism. "Interestingly, infection-induced phospho-SR proteins, particularly SRSF4, SRSF5 and SRSF6, were notably enriched in the Golgi apparatuses and large protein complex fractions at 4 hpi, with virus-induced phosphorylation diminished by 8 hpi (EV-A71)." (PMID 40522993, 2025). "Knockdown of specific SR proteins, including SRSF4, SRSF5, and SRSF6, significantly reduced viral growth, highlighting their critical role in the infection process." (PMID 40522993, 2025).
SRSF4 also shares sentences with these, for which no sentence is quoted: colon adenocarcinoma (3 papers); alcoholic liver diseases (2); HIV-1 infection (2); acute lymphoblastic leukemia (1); alcoholic hepatitis (1); autoimmune lymphoproliferative syndrome (1); Cirrhosis (1); endometrial cancer (1); fibrosis (1); Huntington disease (1); lymphopenia (1); oligodendroglioma (1); steatosis (1); virus infection (1).